TREM2 (triggering receptor expressed on myeloid cells 2)
Diseases named in the same sentence as TREM2 in open-access papers (continued):
Sharing a sentence is not in itself a finding about the gene and the disease.
Obesity (continued). "Additionally, while our findings provide mechanistic insight into the regulation of TREM2 cleavage in murine models, further validation in human adipose tissue will be essential to establish its relevance in human obesity and metabolic disease." (PMID 41509917, 2026). "Activating the TREM2-mediated DAP12-SYK pathway in ATMs could potentially suppress the onset of obesity." (PMID 41459526, 2025). "STF suppresses the accumulation of metabolically active CD9 or Trem2-expressing ATMs in obesity." (PMID 40244655, 2025). "Similarly, defects in triggering receptor expressed on myeloid cells 2 (TREM2)‐dependent efferocytosis in obesity further highlight the metabolic links to impaired macrophage function." (PMID 41030912, 2025). "Similarly, Trem2+ ATMs (F4/80+CD11b+Trem2+) expand significantly in the eWAT of mice with obesity, most of which also express CD9." (PMID 39071288, 2025). "Nowadays, TREM2 has attracted much attention from researchers in the fields of neurodegenerative diseases, neuroinflammation, immunity, cardiac dysfunction, atherosclerosis, metabolic diseases (such as obesity), and cancer 3, 5-9." (PMID 39113887, 2024). "Upregulation of TREM2 has been demonstrated to mitigate insulin resistance induced by obesity." (PMID 38053837, 2023). "Hence, Trem2 expression limits obesity-induced metabolic dysfunction, possibly by promoting the removal of dysfunctional defective adipocytes by ATMs." (PMID 36994095, 2023). "In addition, the pathogenesis of AD is influenced by not only abnormal peripheral lipid metabolism but also TREM2-affected metabolic diseases, such as obesity, hypercholesterolemia, atherosclerosis and NAFLD." (PMID 35658903, 2022). "Although their functions have not been directly investigated, TREM-2 loss remodels ATM populations in obesity and enhances weight gain and adiposity." (PMID 34876704, 2022). "However, bone marrow transplantation experiments by another group argued that hematopoietic-expressed TREM2 is dispensable for obesity-induced metabolic dysfunction, including insulin resistance." (PMID 36119080, 2022). "Additionally, inactivation of the Trem2-related LAM program also led to hypercholesterolemia, which is a complication of obesity and an independent risk factor for AD." (PMID 35658903, 2022). "Moreover, TREM2/DAP12 has been shown to induce obesity by promoting adipogenesis and upregulating the expression of adipogenic regulators within adipocytes via WNT10b/β-catenin signaling." (PMID 33980160, 2021). "Functional characterization discovered that Trem2 is not merely a characteristic marker, but also an essential driver of the LAM molecular program, as they showed that Trem2-knockout mice exhibit HFD-induced obesity, glucose intolerance, insulin resistance, and dyslipidemia." (PMID 32635651, 2020). "The formation of LAM cells in CLS in adipose tissue is driven by Trem2 signaling, and knockout of Trem2 in bone marrow cells deteriorated the metabolic outcomes of obesity, suggesting that Trem2+ LAM cells are crucial for the prevention of metabolic disorders upon loss of adipose tissue homeostasis." (PMID 32646451, 2020). "TREM2 gene expression was upregulated in adipose tissue in obesity animal models." (PMID 32982666, 2020). "Moreover, given that the strong impact of TREM2 on macrophage functional polarization, further studies are warranted to understand the role of TREM2 in chronic inflammatory diseases such as atherosclerosis, obesity, and carcinogenesis." (PMID 33037186, 2020). "Thus, an animal model with TREM2 conditional knockout (cell-specific knockout) in adipocytes and/or macrophages is warranted in future experiments to delineate the effect of TREM2 on obesity induced insulin resistance." (PMID 31477129, 2019). "Our study suggested that TREM2 may act as a novel biomarker and potential therapeutic target of obesity and insulin resistance." (PMID 31477129, 2019).
Obesity (continued). "In conclusion, our data demonstrated that TREM2 may function as a feedback mechanism to inhibit obesity-induced insulin resistance." (PMID 31477129, 2019). "In animal models of obesity, TREM2 gene expression was up-regulated in adipose tissue." (PMID 31477129, 2019). "This study aims to investigate whether TREM2 regulates obesity-induced insulin resistance via modulating adipose tissue remodeling in mice of high-fat diet (HFD)." (PMID 31477129, 2019). "Moreover, since TREM2 is also expressed in the brain, central nervous system–derived sTREM2 may additionally account for the elevated circulating levels observed in obesity." (PMID 41509917, 2026). "However, the precise role of TREM2 in adipose tissue homeostasis remains unclear, with conflicting reports suggesting both protective and deleterious effects in the context of obesity." (PMID 41509917, 2026). "Targeting this pathway by limiting TREM2 shedding through ADAM10/17 inhibition may represent a promising therapeutic approach for mitigating adipose tissue inflammation and systemic metabolic dysfunction associated with obesity." (PMID 41509917, 2026). "As TREM2+ macrophages have been implicated in pathophysiological tissue remodeling involving aberrant lipid metabolism, our results indicate that TM4SF19 might be targeted for treating a large class of obesity-associated metabolic diseases." (PMID 38555350, 2024). "TREM2 might represent an attractive therapeutic target in cardiometabolic disease, as, in addition to its proposed beneficial roles in obesity and other lipid-driven diseases, such as NASH, activating TREM2 signaling may limit plaque necrosis and promote stabilization of atherosclerotic lesions." (PMID 38974464, 2024). "The LAM/DAM signature in VAT samples is elevated by HFD and appears to be a Trem2-dependent uniform response and responsible, at least initially, for the clearance of injured cells and damaged tissue, resolution of inflammation, and improvement of metabolic changes in obesity." (PMID 38685031, 2024). "However, we suggest that, taken together with the experimental data in mice in3,4, our findings warrant additional studies investigating the role of TREM2 in human obesity, especially regarding the intriguing gender-specific effects it may exert." (PMID 36627355, 2023). "Additionally, TREM2-expressing macrophages in the adipose tissue have been shown to prevent obesity and adiposity, which could influence the development of hepatic steatosis." (PMID 37961666, 2023). "CD9 and Trem2 were the plasma membrane markers of this pro-inflammatory, lipid-associated macrophage, and the lean mice receiving the CD9 + macrophages from obese mice displayed severe metabolic disorders, which indicated the causality between this macrophage subtype and obesity." (PMID 37892414, 2023). "In addition, blocking Trem2 signaling restrained HFD-induced obesity in both WT and TG mice." (PMID 35658903, 2022). "Therefore, in addition to discussing the effects and mechanisms of TREM2 on obesity and its complications in detail, we will also discuss the possibility that TREM2 influences the pathogenesis of AD by affecting the inflammation and IR induced by abnormal peripheral lipid metabolism." (PMID 35658903, 2022). "Moreover, by comparing the results obtained from Trem2 TG mice and Trem2 blockade mice, these authors proposed that Trem2 may exacerbate adipocyte hypertrophy, inflammation, and IR during obesity." (PMID 35658903, 2022). "Thus, these researchers proposed that Trem2 may promote diet-induced obesity by regulating the Wnt10b/b-catenin signaling pathway and adipogenic regulators." (PMID 35658903, 2022). "However, although the interactions among inflammation, insulin signaling and lipid metabolism have been widely discussed, it is unclear whether the effect of TREM2 on obesity is achieved by affecting these concomitant factors." (PMID 35658903, 2022).
Obesity (continued). "Thus, the effect of TREM2 on obesity and its complications may be a possible mechanism by which TREM2 influences peripheral lipid metabolism." (PMID 35658903, 2022). "Hence, we hypothesize that TREM2 may act as a feedback protective mechanism to curb obesity induced-insulin resistance via regulating adipose tissue remodeling." (PMID 31477129, 2019). "However, it is unknown whether TREM2 regulates obesity-induced insulin resistance via adipose tissue remodeling." (PMID 31477129, 2019). "This study aimed to investigate the role of TREM2 in adipose tissue inflammation and metabolic dysfunction during high-fat diet (HFD)–induced obesity." (PMID 41509917, 2026). "They found that Trem2 − / − mice fed a HFD showed increased body weight, adipocyte hypertrophy, inflammation and IR, indicating that Trem2 plays a protective role in obesity." (PMID 35658903, 2022). "In summary, the presence of TREM2+CD9+ adipoclasts or adipoclasts precursors seems to correlate with WAT inflammation and the severity of obesity-related pathologies." (PMID 34794433, 2021). "TREM2 is discussed as driver in CLS formation and CD11c expression of ATMs in different obesity models." (PMID 34091595, 2021). "Thus, although TREM2 is important for adipocyte differentiation in cell culture, its expression in ASC is dispensable for WAT remodeling and metabolic health during obesity." (PMID 42109717, 2026). "Similarly, in high-fat diet (HFD) induced obesity mouse models, the expression of Lipoprotein Lipase (LPL) and APOE in adipose tissue macrophages is upregulated through a TREM2-dependent mechanism." (PMID 40636122, 2025). "However puzzlingly, the described ATM populations appear to overlap; for example, TREM-2+ LAMs highly express CD9, and the presence of ATMs is dynamic during obesity progression, with some populations increasing or decreasing over time." (PMID 34876704, 2022). "This study explained that IR and glucose intolerance in obesity were attenuated by TREM2 expressed on nonhematopoietic cells." (PMID 35658903, 2022). "Notably, TREM2+ and CD9+ LAMs were found to be part of CLS and their frequency increased with obesity in mice and humans with a shift toward a pro-inflammatory polarization characterized by IL-1β and TNF production." (PMID 34794433, 2021). "Therefore, TREM2+ macrophages lose their capacity to efficiently clear dying adipocytes and resolve inflammation, contributing to chronic adipose tissue inflammation during HFD-induced obesity." (PMID 41509917, 2026). "Besides expressing SPP1, we found that SPP1+ TAM also expressed APOC4-APOC2, a gene not reported by previous RCC studies, and TREM2, which has been reported in various biological and pathological processes such as obesity and cancer." (PMID 36423636, 2022). "Because all cells in TREM2−/− mice were TREM2 deficient, we can not distinguish whether TREM2 expressed on ATM or adipocytes plays a more important role in the pathogenesis and etiology of obesity-induced insulin resistance." (PMID 31477129, 2019). "In addition, we found that while only approximately 47% of the CD9+ ATMs (F4/80+CD11b+CD9+) express Trem2, an overwhelming majority (~86.7%) of Trem2+ ATMs (F4/80+CD11b+Trem2+) expresses CD9, corroborating a previous finding that Trem2+ expression emerges after CD9+ ATMs over the course of obesity." (PMID 40244655, 2025). "Furthermore, the role of TREM2 in obesity-induced fatty liver disease should not be overlooked." (PMID 40242752, 2025).
Obesity (continued). "However, recent bone marrow transplantation experiments found that hematopoietic/macrophage-expressed TREM2 reduces adipose hypertrophy in diet-induced obesity, but it exerts no influences on other obesity concomitant factors, such as IR and glucose intolerance." (PMID 35658903, 2022). "However, it is not clear whether the protective effect of Trem2 against hypercholesterolemia is mediated by obesity." (PMID 35658903, 2022).
tauopathy (65 papers, 2017 to 2026). Neurodegenerative disorders involving deposition of abnormal tau protein isoforms (tau proteins) in neurons and glial cells in the brain. "The TREM2 R47H variant offers additional insights into TREM2’s role in the PS19 tauopathy model, although findings remain inconsistent." (PMID 40247363, 2025). "In tauopathy mouse models, TREM2 deficiency impeded microglial uptake of tau fibrils, accelerating transneuronal tau spread." (PMID 41476737, 2025). "TREM2 deficiency has produced both neurotoxic effects and exacerbated tau pathology in a primary tauopathy model as well as neuroprotection with the prevention of brain atrophy without affecting phosphorylated tau levels." (PMID 39219300, 2025). "TREM2 is up‐regulated in the brains of P301S mice, a mouse model of primary tauopathy with neurofibrillary tangles and neuron loss present in multiple brain regions." (PMID 39219300, 2025). "In our previous work, we showed that AD-risk allele TREM2-R47H drives aberrant AKT signaling in microglia in tauopathy mice, and that pharmacological inhibition of AKT prevented tau-induced microglia subcluster and rescued synapse loss." (PMID 41331787, 2025). "In TREM2-deficient P301S tauopathy mice expressing murine APOE, neuroinflammation is reduced, and brain atrophy is mitigated, suggesting a neuroprotective role of TREM2 deficiency." (PMID 40149001, 2025). "In PS19 tauopathy mice, the presence of the TREM2 R47H variant exacerbates brain atrophy specifically in 9- to 10-month-old female APOE4 mice, while male mice remain unaffected." (PMID 40247363, 2025). "In a TBI‐induced tauopathy mouse model, TREM2 deficiency increased microglial accumulation in the corpus callosum in the chronic phase, which resulted in exacerbated WMI." (PMID 38649789, 2024). "In the THY-Tau22 transgenic murine model of tauopathy, TREM2 deficiency decreased microglial activation, which exacerbated pathological changes in later stages." (PMID 37489359, 2023). "In the THY-Tau22 mouse model of tauopathy, another study revealed that TREM2 deficiency worsens tau pathological changes in later stages owing to the lower microglial activation rate." (PMID 37489359, 2023). "The genetic association of TREM2 variants with AD has prompted in depth studies on the impact of TREM2 on microglia responses to pathological features of AD, including Aβ plaques, tauopathy and demyelination, which will be reviewed in the following sections." (PMID 36564824, 2022). "Conversely, tauopathy studies in PS19 mouse models suggest that TREM2 deficiency attenuates neuroinflammation, while TREM2 itself protects against tau-mediated neurodegeneration." (PMID 35741054, 2022). "Studies using the PS19 mouse model of tauopathy have demonstrated that TREM2 signaling aggravates NFT pathology, associated with pro-inflammatory, Il-1β+ microglia." (PMID 35764973, 2022). "A recent study showed that expressing the R47H risk allele in a humanized Trem2 mouse model lowers the expression of C1q at synapses which in turn protects them from damage in the setting of a tauopathy mouse model." (PMID 33172468, 2020). "Some authors, studying the role of TREM2 in tauopathies, have reported that TREM2 deficiency exacerbates tau pathology [e.g., tau hyperphosphorylation and aggregation via activated neuronal stress kinases]." (PMID 33343298, 2020). "It is also logical to compare the effects of TYROBP or TREM2 deficiency on tauopathy, although this is somewhat difficult due to discrepant findings reported to date from Trem2 KOs crossed with mouse models of tauopathy." (PMID 30283031, 2019). "Taken together, these 2 studies suggest that partial or normal TREM2 function contributes to tauopathy as well as tau-mediated damage and that complete loss of function also decreases tau-mediated brain injury." (PMID 30572908, 2018).
tauopathy (continued). "TREM2 deficiency in the setting of pure tauopathy limits gliosis and neuroinflammation, as well as protecting against brain atrophy, suggesting that TREM2 facilitates a microglial response to tau pathology and/or tau-mediated damage in the brain." (PMID 29440986, 2018). "The current study demonstrates that TREM2 deficiency leads to worsened tau pathology, altered microglial reactivity, and robust signaling abnormalities in the hTau mouse model of tauopathy." (PMID 29037207, 2017). "Here we report that TREM2 deficiency leads to accelerated and exacerbated hyperphosphorylation and aggregation of tau in a humanized mouse model of tauopathy." (PMID 29037207, 2017). "While the TREM2 Arg47His mutation was found to be largely associated with an increased risk for AD, its role in tauopathies could present a more complex picture, since some studies suggested that the mutation may have a neuroprotective effect." (PMID 40806186, 2025). "In Aβ-containing models, TREM2 deficiency exacerbates tau pathology, whereas in pure tauopathy mouse models, it may attenuate tau propagation." (PMID 41168805, 2025). "Moreover, the effects of TREM2 R47H variant on tauopathy were described using the same TREM2CV and TREM2R47H mouse lines crossing with PS19 mice." (PMID 38462606, 2024). "However, it has also been shown that TREM2 deficiency attenuates neuroinflammation and prevents neurodegeneration in a mouse model of tauopathies." (PMID 38020891, 2023). "Considering the genetic association of TREM2 p.H157Y with AD risk, we speculate TREM2 H157Y in humans might increase AD risk through an amyloid-independent pathway, such as its effects on tauopathy and neurodegeneration which merit further investigation." (PMID 36721205, 2023). "Similarly, TREM2 deficiency promotes tau pathology and aggregation via enhanced kinase activation in the mouse model of tauopathy." (PMID 36389767, 2022). "However, the role of TREM2 in AD etiopathogenesis is complicated by the conflicting impacts of Trem2 deficiency on brain amyloidopathy and tauopathy in multiple lines of mouse models." (PMID 33557250, 2021). "TREM2 deficiency and disease-associated TREM2 have been linked to increased tauopathy." (PMID 32973488, 2020). "Similarly, the impact of TREM2 deficiency on tau pathology is unclear with studies suggesting that TREM2 deficiency exacerbates the tau pathology or on the opposite prevents the neurodegeneration induced by the tauopathy." (PMID 31649511, 2019). "In addition, differential effects of partial and complete loss of TREM2 have been observed in a mouse model of tauopathy showing protective effects of complete TREM2 deficiency but exacerbation of the tau pathology in TREM2 haploinsufficient mice." (PMID 31649511, 2019). "Given the results of the current studies, it will be important to understand the effects of human TREM2 and human TREM2 variants in both pure tauopathy models that develop tau pathology and neurodegeneration as well as the effects of TREM2 in models that develop both Aβ and tau pathology." (PMID 30572908, 2018). "By contrast, the current study demonstrates that TREM2 deficiency results in robustly enhanced intraneuronal tau phosphorylation, aggregation, and kinase dysregulation in the hTau mouse model of tauopathy, suggesting opposing roles in modulating the two cardinal hallmarks of AD pathology." (PMID 29037207, 2017). "However, in later AD stages or in tauopathies, the partial loss of TREM2 function may be protective by reducing excessive microglial activation and aberrant synaptic phagocytosis." (PMID 40806186, 2025). "TREM2, a transmembrane protein expressed exclusively on microglia in the brain, may be implicated in the pathology of neuroinflammation and concomitant neurodegeneration such as AD and tauopathy, as shown in some in vivo studies." (PMID 37092223, 2023).